CSF1 (colony stimulating factor 1)
Diseases named in the same sentence as CSF1 in open-access papers (continued):
Sharing a sentence is not in itself a finding about the gene and the disease.
cancer (continued). "In addition, Il18, Tnf, Ptgs2, Cd47, Cxcl1, and Csf1 were more highly expressed in STOSE tumors, including in the cancer cells, supporting the influence of TAMs in these tumors." (PMID 36311166, 2022). "While macrophages treated with AREG or HB-EGF without CSF-1 did not survive the treatment period, macrophages treated with rCSF-1 alone induced cancer cell invasion, and adding rHB-EGF or rAREG did not further enhance this effect." (PMID 35998057, 2022). "Indeed, numerous studies have reported that the overexpression of CSF-1 and CCL2 is correlated with poor prognosis in numerous human cancers, including breast, ovarian, endometrial, prostate, hepatocellular, and colorectal cancer, etc.." (PMID 34207286, 2021). "Matched TWIST1-proficient versus TWIST1-deficient cells embedded into Matrigel plugs were injected subcutaneously to mice and the resulting plugs were harvested 14 days later and processed for IHC staining to analyze the degree of cancer cell infiltration and TWIST1 and CSF1 protein expression." (PMID 33466385, 2021). "Overall, the activity of TAMs in cancer is usually pro-tumorigenic, closely related to the colony-stimulating factor (CSF)-1 secretion by cancer cells that recruit TAMs, which in turn, by releasing EGF, edit cancer cells and favour cell migration, extravasation and metastases." (PMID 32423420, 2020). "Cancer cells secrete chemokine (C-C motif) ligand 5 (CCL5) to attract immunosuppressive Tregs, C-X-C motif chemokine 5 (CXCL5) to recruit neutrophils and colony-stimulating factor-1 (CSF-1) to attract macrophages." (PMID 32397303, 2020). "Because there is no published research investigating the role of CSF-1 in UTUC, we aim to examine the association between the clinicopathological behavior of UTUC and CSF-1 expression in cancer tissues." (PMID 31565097, 2019). "Not surprisingly, high expression of CSF-1R or its ligand, CSF-1, in cancer, including pancreatic ductal adenocarcinoma (PDAC), is associated with poor prognosis and an immunosuppressive TME." (PMID 31439034, 2019). "Next, we explored whether the CSF-1 expression in human UTUC tissue samples was correlated to disease-free survival and cancer-specific survival of patients using Kaplan-Meier survival analysis." (PMID 31565097, 2019). "Furthermore, H19 regulated many other cancer-related genes in this network, such as AKT3, CSF1, MET, COL1A1, COL5A1, WWTR1, EPHB4, and TMPRSS3." (PMID 31164794, 2019). "Cancer cell migration itself is controlled through a paracrine loop involving colony stimulating factor 1 (CSF1), epidermal growth factor (EGF), and their receptors, which are differentially expressed on carcinoma cells and macrophages, resulting in movement of cancer cells toward macrophages." (PMID 31572718, 2019). "It was reported that poor prognosis is linked to increased levels of CD163 (TAM marker with M2 phenotype), CSF-1 (colony-stimulating factor-1), major regulator of macrophage lineage, and Arginase-1 (Arg-1) – markers of TAM’s activity – in several cancers including the HPV-related ones." (PMID 29976244, 2018). "We found that already at these early stages of progression, HER2+ cancer cells upregulated expression of Ccl2 but not Csf2, Csf1, Il1β, and Il6." (PMID 29295986, 2018). "Paracrine loops of colony-stimulating factor-1 (CSF-1)/EGF and granulocyte-macrophage colony-stimulating factor (GM-CSF)/CCL18 between carcinoma cells and macrophages have been shown to lead to increased carcinoma cell invasion." (PMID 28143526, 2017). "In contrast, strong positive expression of CSF1 was identified in the cytoplasm of cancer tissues, but only weak staining was observed in the non-cancerous lung tissues." (PMID 27107415, 2016). "Additionally, proteins that are overexpressed in cancer cells are among the targets of down-regulated miRNAs in different treatment conditions, which includes Wnt3A, PPARα, UCP2, CSF1, and MED1." (PMID 24387052, 2014).
cancer (continued). "Indeed, we found that miR-146a over-expression reduced expression of several cytokines and growth factors with a known role in cancer development; IL-8, IL-23A, CCL5, CSF-1 and PDGFB." (PMID 22992343, 2012). "For example, blocking the binding of colony-stimulating factor 1 (CSF-1) to its receptor (CSF-1R) expressed on monocytes/macrophages with an anti-CSF-1R antibody, Emactuzumab, reduced the number of infiltrated TAMs and increased the CD8+/CD4+ T cell ratio in mouse models for cancer." (PMID 37046671, 2023). "Cancer cells can secrete both monocyte and macrophage chemotactic factors, e.g., C-C motif chemokine ligand 2 (CCL2), as well as the agents that accelerate the maturation of these cells and activate them, e.g., the colony stimulating factor 1 (CSF1) and CSF2, and also inhibit their chemotaxis." (PMID 38001676, 2023). "In our study, the expression trend of CSF1 was not consistent across cancer types." (PMID 37097499, 2023). "The CSF1, under physiological conditions, plays a role in cell survival, proliferation, differentiation, and functions of the mononuclear cells, and therefore its higher expression in patients without cancer is not surprising." (PMID 36209194, 2022). "In addition, a significantly positive correlation (p < 0.001) is also observed between CSF-1R+ carcinoma cells and macrophages expressing CSF-1R and CD163, supporting the plausible existence of a CSF-1/CSF-1R paracrine signaling mechanism as has been suggested in the preclinical studies." (PMID 34830923, 2021). "During tumorigenesis, cancer cells secrete Colony Stimulating Factor (CSF–1) to recruit macrophages; in turn, recruited macrophages release glial derived neurotrophic factor (GDNF) that activates RET (REarranged during Transfection) on cancer cells to promote cancer migration and nerve invasion." (PMID 31248001, 2019). "However, the roles of IL34 and CSF1 at homeostasis or in the context of inflammatory diseases or cancer in wild-type mice have not been clarified in vivo." (PMID 31552020, 2019). "During cancer development, macrophages are recruited in the tumor stroma by several inflammatory mediators, such as chemokines: CCL2 (also known as MCP-1), CCL5, CXCL12 (also known as SDF-1), cytokines: vascular endothelial growth factor (VEGF), CSF1, and activated complement elements." (PMID 29675018, 2018). "In addition, FOXC2, SALL4, CSF1 and BMI1 mRNA levels were also increased in Hep3B-TFF3 cells, all of which have recently been suggested to be involved in promoting CSC-like characteristics in various cancer cells." (PMID 28445151, 2017). "Notably, the CSF1/CSF1R signaling axis is overexpressed in several epithelial cancers, and there is clinical evidence that this pathway plays a role in radio-resistance of some cancers." (PMID 24019961, 2013). "In addition, it is also reported that NF-κB activation is known to trigger cancer cell proliferation and angiogenesis by regulating the gene expression of B-cell lymphoma 2 (Bcl-2), vascular endothelial growth factor (VEGF), and colony stimulating factor 1 (CSF1)." (PMID 36555124, 2022). "TAM membrane-coated nanoparticles could scavenge CSF1 secreted by cancer cells due to the high CSF1R content on the TAM membranes, blocking the interaction between TAMs and cancer cells and thereby enhancing the efficacy of the nanoparticles for cancer immunotherapy." (PMID 35216342, 2022). "However, the mechanism of CSF-1 and CSF-1R in GI malignant tumors is still not clear, and the mechanism of how inflammatory immune cells participate in the occurrence and development of malignant tumors is not perfectly defined." (PMID 34729112, 2021). "However, there are no reports of Vav1 stimulation by CSF1 in cancer cells." (PMID 25313137, 2014). "In chemotaxis assays, fusion hybrids migrated toward colony-stimulating factor 1 (CSF1) or stromal cell-derived factor-1 (SDF1) at multiple concentrations, whereas unfused MC38 cancer cells showed no response to either chemoattractant." (PMID 37427108, 2023).
cancer (continued). "In addition to CSF1, IL-4 from CD4+ T cells is necessary to activate TAMs to produce EGF and without CD4+ T cells, TAMs are unable to induce cancer cell migration and metastasis." (PMID 29220404, 2017). "Among the genes that were down-regulated in the absence of Vav1 was CSF1, as well as several genes whose products might participate in signaling events, including lysyl oxidase (LOX), known to participate in cancer development." (PMID 25313137, 2014). "For administration to cancer patients, a mAb which could inhibit CD115 function without preventing CSF-1 capture and degradation may be preferable to a ligand-competitive mAb." (PMID 24019914, 2013).
infection (164 papers, 2006 to 2026). The state of being infected such as from the introduction of a foreign agent such as serum, vaccine, antigenic substance or organism. "The kidneys of IL-34-MΦ-enriched frogs exhibited lower transcript levels of the FV3 immediate early (icp18), delayed early (rad2) and late (mcp) genes than the kidneys of CSF-1-MΦ-enriched frogs at three dpi and the loss of this protection with infection time." (PMID 34835105, 2021). "Infection-associated tissue damage, such as that seen in the CSF-1-MΦ-enriched and FV3-infected frogs, is often accompanied by and is attributed to infiltrating inflammatory cells such as granulocytes and MΦs." (PMID 34835105, 2021). "Using the Xenopus laevis frog model, we previously established that amphibian MΦs differentiated by IL-34 offer anti-FV3 protection, whereas CSF-1-MΦs render the animals significantly more susceptible to FV3 infections." (PMID 34835105, 2021). "Accordingly, we suggest that CSF1-Fc treatment has potential to promote rapid maturation of innate immunity in neonates at high risk of infection." (PMID 29351395, 2018). "Macrophage colony-stimulating factor (M-CSF, CSF1) is a cytokine for attracting macrophages to infection sites to defend against different pathogenic infections." (PMID 29844933, 2018). "However, infection reduced the expression of several chemokines upregulated by 4T1, including monocyte recruitment factors Csf1, Ccl3, Ccl6, Ccl9, Ccl24 and EMT-associated Cxcl1." (PMID 40547518, 2025). "A possible interpretation of low infection in DCs could be that while BMDMs were cultured in the presence of chicken CSF-1, BMDCs were cultured with chIL-4 and chCSF-2, leading to differential transcription profiles in these two cell types, which might affect their susceptibility to infection." (PMID 36422592, 2022). "CSF2-cFLiMo–derived alveolar macrophages are superior to CSF1-cBMM–derived alveolar macrophages in reconstitution of empty alveolar macrophage niches and prevention of morbidity to infection with influenza virus." (PMID 35393945, 2022). "In turn, our present work indicates that while the IL-34-MΦ-mediated anti-FV3 protection is short-lived, the increased frog susceptibility conferred by CSF-1-MΦs extends into chronic FV3 infections, exacerbating the infection outcomes." (PMID 34835105, 2021). "This enrichment would thus provide further means for FV3 persistence and dissemination, possibly due to these rIL-34-enriched cells also adopting a CSF-1-MΦ-like phenotype with infection time." (PMID 34835105, 2021). "There was a robust correlation between SARS-CoV-2 transcripts and the IFN-γ-induced chemokine Cxcl-10 (IP-10) and to a lesser extent Csf1, Ccrl2, and Ccl5, which are all involved in the recruitment of immune cells to the site of infection." (PMID 34319784, 2021). "Our findings indicate that the frog CSF-1-MΦs result in more prominent kidney FV3 infections, which develop into greater reservoirs of lingering FV3 marked by infiltrating leukocytes, fibrosis, and overall immunosuppressive states." (PMID 34835105, 2021). "Given the central role of macrophages and monocytes in infection, we assessed the consequences of neutralizing CSF1 and/or IL34 in mice infected with Listeria monocytogenes." (PMID 31552020, 2019). "CSF-1 expression is induced by uropathogenic E.coli infection and has a critical role in bacterial clearance during infection." (PMID 31366318, 2019). "Of particular interest during infection with L. monocytogenes, CSF-1 targeting of trophoblasts induces production of neutrophil chemoattractants (KC) and macrophage inflammatory protein-2 (MIP-2)." (PMID 29799503, 2018). "Expression of Csf1-lnc and Socs2-lnc was significantly reduced during infection with the ROP16 deletion mutant (RH∆16) compared to RH." (PMID 30301916, 2018).
infection (continued). "Neutrophils are recruited to sites of infection by cytokines such as IL-6 and, in turn, secrete chemokines such as colony stimulating factor-1 (CSF-1) and MCP-1 to recruit macrophages." (PMID 29799503, 2018). "The systems biology analysis identified multiple immune system and inflammation molecules (e.g., STAT3, STAT1, CEBPB, JUN, IGF1, SPP1, NFKB2, IL-1β, and CSF1) as master regulators that are activated upon infection." (PMID 26865111, 2016). "We also noted changes in the expression of transforming growth factor-1 (tgfβ1) in the SN starting at 7 days post-infection (dpi) that was sustained through 21 dpi, coupled with increases in arginase-1 (arg1) and csf1, M2 markers for microglia." (PMID 25861024, 2015). "We subsequently identified CSF1-dependent mechanisms to be responsible for the residual proliferative expansion of these cells during infection." (PMID 25319331, 2014). "Genes that were down-regulated genes at 24h post infection included inflammatory and anti-pathogen genes (CSF1 and USP2) and the cell apoptosis and death genes (MICB, BUB1B, ITGB2, UBB and BIRC3)." (PMID 23527143, 2013). "In particular, the significant over-expression of the Csf1, Lefty1, Ccrl2, Gdf3, Il-10 and Ccl8 genes (1.8–5.8 fold increases) was seen at day 9 post-infection." (PMID 23861742, 2013). "In this study, expression levels of IL-4, IL-10, IL-13 and TNF-α were significantly up-regulated while the expression levels of IL-1β,IL-18,IFN-γ, IL-2, IL-15, IL-17F, IFN-α, IFN-β, IL-3 and CSF-1 were markedly decreased in PBMCs at all stages of infection." (PMID 24358317, 2013). "The upregulation of ISG15, CXCL-10, ADAM8, and CSF1 was found after infection with vPdR-36U, which could contribute to the generation of mild CSF forms." (PMID 40006915, 2025). "Interestingly, DEGs associated with neurodegenerative diseases, such as NLRP3, CSF1, and A2M, exhibit higher expression in the ITA infection group." (PMID 40723822, 2025). "Macrophage speeds for our 2D/3D infection model (7.61 × 10−4 μm/s, 3.8 × 10−4 μm/s) and 3D control (2.75 × 10−4 μm/s) were comparable to macrophage speeds observed for CSF-1-starved cells (~6.39 × 10−4 μm/s), which also exhibited a more rounded morphology similar to our 3D and infected 2D cultures." (PMID 41011358, 2025). "Additionally, we observed downregulation of MCP-1 and CSF1 which are critical in recruiting, differentiating, and expanding monocytes at sites of infection." (PMID 37795301, 2023). "Perhaps future frog FV3 infection studies in which the proportions of CSF-1- and IL-34-MΦs are altered, may shed additional light upon the dynamics and consequences of the recruitment of distinct leukocyte subsets into virally infected frog tissues." (PMID 34835105, 2021). "Given the central role of macrophages in fighting infection, long-term blockade of the CSF1R/CSF-1/IL-34 axes could compromise the response to infection." (PMID 32581720, 2020). "Expression levels of interleukin (IL)-4, IL-10, IL-13 and tumor necrosis factor (TNF)-α were significantly up-regulated while interferon (IFN)-α, IFN-β, IFN-γ, IL-1β,IL-2, IL-3, IL-15, IL-17F, IL-18 and colony-stimulating factor (CSF)-1 were markedly decreased in PBMCs at all stages of infection." (PMID 24358317, 2013). "Downregulated secretion of MCP-1 and CSF1 in BECs exposed to T. pallidum may attenuate the migration of monocytes to sites of T. pallidum colonization and allow T. pallidum to evade clearance and disseminate during early infection." (PMID 37795301, 2023). "It will be interesting to explore these notions further in the context of progressing FV3 infections and examine whether this virus manipulates the frog host tissue ratios away from the IL-34-MΦs towards the CSF-1-MΦs within and beyond the timeframe of the FV3 infection studies presented here." (PMID 34835105, 2021).